RNU6-264P (RNA, U6 small nuclear 264, pseudogene)
Gene: Small nuclear RNA gene on chromosome 9 (19,073,843 to 19,073,946, forward strand). Ensembl gene ENSG00000252943.
Homologues: Orthologues: chimpanzee U6 (84% identical), macaque U6 (81% identical), rat LOC120094561 (66% identical). Paralogues in human: RNU6-1131P (75% identical), RNU6-189P (75% identical), RNU6-1050P (73% identical), RNU6-1122P (73% identical), RNU6-242P (73% identical), RNU6-263P (73% identical), RNU6-28P (73% identical), RNU6-47P (73% identical), RNU6-543P (73% identical), RNU6-558P (73% identical), RNU6-838P (73% identical), RNU6-97P (73% identical), and 1280 more.